PNPLA3 (patatin like domain 3, 1-acylglycerol-3-phosphate O-acyltransferase )
Diseases named in the same sentence as PNPLA3 in open-access papers (continued):
Sharing a sentence is not in itself a finding about the gene and the disease.
Cirrhosis (continued). "Percentage and median age of participants with cirrhosis/advanced fibrosis, with central obesity (CO) alone or in combination with diabetes (DM), excess alcohol consumption (Alc) or 2 risk alleles of PNPLA3 rs738409 (SNP) in males and in females." (PMID 26950933, 2016). "The PNPLA3-148 M variant also increases the risk of cirrhosis in alcoholics (10, –, 12), suggesting that alcoholic liver disease and NAFLD share common pathogenic elements." (PMID 27013658, 2016). "When the same analysis was carried out excluding individuals with cirrhosis at baseline the presence of the PNPLA3 rs738409 G showed a trend to association with significant LSP (adjusted p-value = 0.053; adjusted odds ratio = 2.73; 95% CI = 0.98–7.56)." (PMID 27973562, 2016). "Factors that remained independently related to cirrhosis in the multivariate analysis were the presence of the PNPLA3 rs738409 G allele, older age, lower HCV viral load and total cholesterol levels." (PMID 27973562, 2016). "In conclusion: rs430397 in GRP78 and rs738409 in PNPLA3 are risk factors for the development of HCC in a Southern Italian population of cases with predominantly HCV-related cirrhosis." (PMID 27888630, 2016). "This analysis showed that older age (OR = 1.05; 95% CI: 1.02–1.09; p = 0.0034), and PNPLA3 genotype GG (OR = 3.35; 95% CI: 1.13–9.91; p = 0.0291) were factors independently associated with progression to cirrhosis." (PMID 25713769, 2015). "Age, gender, and PNPLA3 genotype were assessed for the factors possibly associated with the progression to cirrhosis by multivariable regression analysis." (PMID 25713769, 2015). "In this study, we demonstrated that a PNPLA3 polymorphism was associated with the progression of fibrosis to cirrhosis." (PMID 25713769, 2015). "The sex-specific association of PNPLA3 SNPs with HBV-related cirrhosis also deserves further investigation." (PMID 25337145, 2014). "In ALD&NAFLD patients, the PNPLA3 148M allele was associated with younger age, shorter history of cirrhosis, less advanced (Child A) cirrhosis at HCC diagnosis, and lower HCC differentiation grade (p<0.05)." (PMID 24155878, 2013). "Conversely to the SREBP1c variant, the PNPLA3 p.I148M SNP is associated with more advanced stages of liver fibrosis and increases the risk of cirrhosis." (PMID 24152445, 2013). "Recently, the PNPLA3 genotypes in addition to diabetes status were found to identify patients at a higher risk of cirrhosis among those at an indeterminate risk of MAFLD in two Caucasian cohorts, the clinical role of which has not been reproduced in a Korean biopsy-proven MAFLD cohort." (PMID 40141404, 2025). "In our study, patients with MASLD with a higher GRS exhibited increased risk of cirrhosis, showing a two-fold higher combined effect compared with PNPLA3 alone, suggesting a potential role of GRS in stratifying high-risk patients for MASLD-related cirrhosis development." (PMID 40995436, 2025). "Also, individuals with ALD who are homozygous for the PNPLA3 I148M genetic variant have a 2.2–2.4‐fold risk of cirrhosis." (PMID 40179033, 2025). "In this study, PNPLA3 was associated with the development of both cirrhosis and HCC." (PMID 40995436, 2025). "We observed that rare coding variants (pLoF + missense) and pLoF variants (excluding missense) in PNPLA3 were both nominally associated with increased cirrhosis risk (pLoF + missense—OR: 1.86; 95% CI: 1.19–2.90; P = 6.0 × 10−3; pLoF—OR: 2.97; 95% CI: 1.09–8.15; P = 0.034)." (PMID 38632349, 2024). "Interestingly, the majority of SNPs identified as risk factors for alcohol-associated cirrhosis in recent GWAS reside in/around the genes related to lipid metabolism and lipid droplet biology (PNPLA3, HSD17B13, FAF2 and TM6SF2)." (PMID 37887024, 2023). "The PNPLA3 G/G genotype is associated with an increased rate of cirrhosis in NAFLD." (PMID 36166317, 2022).
Cirrhosis (continued). "Genetic variants, such as I148M in the patatin-like phospholipase domain-containing protein 3 (PNPLA3) gene, may play an important role in modulating cirrhosis and HCC risk." (PMID 36190732, 2022). "In addition, no statistically significant increasing trend of hepatic fibrosis or cirrhosis was observable with increase in number of PNPLA3 and TM6SF2 risk alleles." (PMID 36028802, 2022). "The most validated so far is the variant p.I148M in 1-acylglycerol-3-phosphate O-acyltransferase (PNPLA3), associated with higher triglyceride levels, as well as with an increased risk of non-alcoholic steatohepatitis, cirrhosis decompensation, HCC development, and mortality." (PMID 36233142, 2022). "In addition, the presence of rs738409 in PNPLA3 is associated with an increased risk of HCC development in patients with cirrhosis due to ALD, with an estimated risk of twofold after adjusting for other confounders (e.g., age, sex, body mass index)." (PMID 34068269, 2021). "Our results suggest that PNPLA3 rs738409 G allele carriage may be associated with a faster progression of HCV cirrhosis to chronic liver failure." (PMID 31527889, 2019). "In conclusion, our results show that the pronounced liver steatosis and fibrosis in PNPLA3 rs738409 G allele carriers with HCV genotype 1b cirrhosis may have a real impact on the timing and need of liver transplantation." (PMID 31527889, 2019). "PNPLA3 rs738409 GG gene variant carriers have 73% more liver fat, a 3.2-fold higher risk of liver necro-inflammation, and a 1.9-fold higher risk of cirrhosis than PNPLA3 wild-type CC genotype carriers." (PMID 31447675, 2019). "Only the PNPLA3 rs738409 genetic marker was associated with cirrhosis." (PMID 27973562, 2016). "Multivariable logistic regression analysis selected older age (OR = 1.06; 95% CI: 1.03–1.09; p < 0.0001), higher body mass index (BMI) (OR= 1.12; 95% CI: 1.03–1.22; p = 0.0082), and PNPLA3 genotype GG (OR = 2.07; 95% CI: 0.97–4.42; p = 0.0599) as the factors independently associated with cirrhosis." (PMID 25713769, 2015). "In this study, we demonstrated that a PNPLA3 gene polymorphism was associated with the progression of fibrosis to cirrhosis and development of HCC, although the association with cirrhosis was only a tendency by multivariable analysis in all the 231 patients studied." (PMID 25713769, 2015). "We also report novel data suggesting that HCCs arising in patients with ALD&NAFLD homozygous for the 148M PNPLA3 allele present earlier during the natural history of cirrhosis, are less differentiated, and have a larger diffusion at presentation, and a worse prognosis." (PMID 24155878, 2013). "On the other hand, the PNPLA3 148M variant had only minor effects on the HCC risk in cirrhosis associated with chronic hepatitis C suggesting that this genetic variant is not a tumour gene per se but only acts in combination with substantial alcohol exposure and hepatic lipid accumulation." (PMID 22087248, 2011). "PNPLA3 genotype may also help predict HCC in the key populations of cirrhosis and at-risk chronic hepatitis B; however, there are minimal data on genetics and longitudinal outcomes in chronic hepatitis B112,113 so we will focus on cirrhosis for the rest of this discussion." (PMID 39774697, 2025). "Therefore, PNPLA3 I148M genotypic information may be informative to refine cirrhosis and HCC risk stratification in the growing populations with heavy alcohol intake and obesity." (PMID 36190732, 2022). "For this case–control study, we previously demonstrated a relationship between PNPLA3 (patatin-like phospholipase domain-containing protein 3) GG status and oxidative DNA damage, which may explain the excessive risk of cancer in patients with cirrhosis." (PMID 31040908, 2019). "However, the role of PNPLA3 in predicting the risk of cirrhosis has been already described." (PMID 30189691, 2018).
Cirrhosis (continued). "PNPLA3 genetic variants appeared to be strongly associated with the increased pathogenesis of MASLD, MASH, cirrhosis, and HCC." (PMID 40507973, 2025). "At an individual level, only PNPLA3 GG genotype was associated with a significantly increased risk of MASLD-related HCC (odds ratio [OR]: 2.805, 95% CI: 1.083–7.264, p = 0.034) and cirrhosis (OR: 6.873, 95% CI: 3.293–14.35, p <0.001)." (PMID 40995436, 2025). "Patients with cirrhosis (n = 242) and the PNPLA3-GG genotype showed a 2.8-fold increase in the odds of developing cirrhotic HCC compared with those with the CC genotype (OR: 2.805, 95% CI 1.083–7.264, p = 0.034)." (PMID 40995436, 2025). "The main genetic determinant is the common PNPLA3 p.I148M variant, which explains a substantial portion of SLD interindividual and interethnic variability, up to a quarter of liability to cirrhosis and liver cancer in the general population." (PMID 40747912, 2025). "The effect of PNPLA3 on HCC risk, as previously reported for cirrhosis development, is also modulated by environmental factors like alcohol use and obesity." (PMID 39412170, 2025). "Genetic markers, such as single nucleotide polymorphisms (SNPs) in genes like PNPLA3 and TM6SF2, have been linked to an increased risk of liver fibrosis and cirrhosis." (PMID 40430206, 2025). "In summary, our findings suggest that SNPs in PNPLA3 and HSD17B13 are associated with MASLD-related cirrhosis development." (PMID 40995436, 2025). "Genomic profiling: Advances in genome sequencing have enabled the discovery of genetic variants (e.g., PNPLA3, TM6SF2) linked to cirrhosis risk and progression." (PMID 40430206, 2025). "If untreated, PNPLA3 I148M homozygosity can lead to a three to four‐fold increased risk of MASH, cirrhosis and up to a 12 times elevated risk of HCC." (PMID 40478199, 2025). "The PNPLA3 rs738409, PRS-MASLD, PRS-cirrhosis, and PRS-cALT were associated with all specific liver outcomes including SLD, cirrhosis and HCC." (PMID 39049959, 2024). "Genetic variants in the I148Met allele of PNPLA3 and the 167Lys allele of TM6SF2 have been shown to be strongly linked to the increase in hepatic fat deposition and the development of cirrhosis and hepatocellular carcinoma." (PMID 36670387, 2023). "In the last decade, an increasing number of events have demonstrated that PNPLA3 rs738409 polymorphism is closely associated with hepatic fat accumulation, ALD, NASH, cirrhosis, and HCC." (PMID 37298640, 2023). "The G allele of the PNPLA3 rs738409 (148M) variant is associated with an increased risk of NAFLD development, and progression of NAFLD to NASH, liver fibrosis, and even cirrhosis." (PMID 35910194, 2022). "Analysis of the common genetic variant p.I148M in the PNPLA3 (adiponutrin) gene, previously detected risk factor for NAFLD, was significantly associated with ALD and ALD-cirrhosis." (PMID 35269779, 2022). "PNPLA3 and TM6SF2 SNPs were associated with both progression to cirrhosis and NAFLD-HCC development, while PDCD1 SNPs were specifically associated with NAFLD-HCC risk, regardless of cirrhosis." (PMID 33808740, 2021). "In this study, we aimed to investigate the contribution of previously implicated genetic risk factors (PNPLA3, TM6SF2, EGF, MTHFR) for the development of cirrhosis and HCC in the Croatian population." (PMID 34640639, 2021). "We replicated known associations of PNPLA3, TM6SF2, HFE and HDS17B13 variants with cirrhosis at genome-wide significance." (PMID 32282858, 2020). "Variant alleles in PNPLA3 and TM6SF2 that decrease risk of cirrhosis have been reported to increase risk for coronary artery disease (CAD)." (PMID 32282858, 2020). "As expected, a higher effect size for rs738409 at PNPLA3 was obtained when only NAFLD plus presence of cirrhosis were compared with healthy controls (OR = 2.0, 95% CI 1.38–2.86, p = 0.0001)." (PMID 31311600, 2019). "In this part of the study we used genotyping data from our previous study on PNPLA3 rs738409 and liver fibrosis/cirrhosis." (PMID 30875804, 2019).
Cirrhosis (continued). "Taken together, our results clearly support the implication of PNPLA3 rs738409 on fibrosis progression and, ultimately, the development of cirrhosis in HIV/HCV coinfection." (PMID 27973562, 2016). "Nowadays, more than 50 studies on the genotyping of PNPLA3 have confirmed the association between the 148M variant and the full range of NAFLD, including simple steatosis, steatohepatitis, cirrhosis, and hepatocellular carcinoma." (PMID 27128907, 2016). "An allele in PNPLA3 (rs738409[G], encoding I148M, prevalence 30%–50% worldwide) increases liver fat (“PNPLA3 NAFLD”) and the risk of hepatic inflammation and fibrosis, cirrhosis and hepatocellular carcinoma (HCC)." (PMID 26556368, 2015). "We found significant associations between EGF, IL28B, and PNPLA3 genotypes and the risk of clinical deterioration in patients with HCV-related cirrhosis." (PMID 25504078, 2014). "The PNPLA3 148M variant is a prominent risk factor for HCC in patients with alcoholic cirrhosis, while its effects are negligible in patients with cirrhosis due to HCV." (PMID 22087248, 2011). "Of note, the distribution of PNPLA3 I148M alleles was similar in healthy controls and patients with HCV-associated cirrhosis and HCV-related HCC giving rise to 22.9%, 25.3% (p = 0.545) and 30.2% (p = 0.071) frequencies of the 148M allele, respectively." (PMID 22087248, 2011). "The ratio of PNPLA3 CG/GG (below 55%) in patients with cirrhosis in these studies is much lower than in our Latin American cohort, which may reflect differences in etiologies and ethnic backgrounds." (PMID 40995436, 2025). "In one prospective study of diabetic individuals, a PRS including PNPLA3, transmembrane 6 superfamily member 2 (TM6SF2) and SERPINA1 was associated with an increased risk of cirrhosis (p = 0.03) and, more interestingly, was associated with advanced fibrosis among those with FIB‐4 < 1.3 (p = 0.03)." (PMID 39412170, 2025). "However, the combined GRS, which includes PNPLA3, demonstrated substantially higher ORs than PNPLA3 alone in identifying patients at high risk for HCC and cirrhosis." (PMID 40995436, 2025). "The lead variants at PNPLA3, TM6SF2, and APOE were either coding or in high LD with a coding variant and have all been previously implicated in the full spectrum of MASLD, including cirrhosis and HCC." (PMID 40823170, 2025). "Notably, this correlation exists independently of PNPLA3, TM6SF2, and MBOAT7, with a stronger association for NAFLD/ALD cirrhosis than other risk factors." (PMID 40004054, 2025). "In the intermediate-risk FIB4 category (1.3–2.67), participants with both highest risk PNPLA3 genotypes (rs738409-GG) and diabetes had an overall incidence of cirrhosis that was not significantly different from that of individuals with high FIB4 (>2.67)." (PMID 39774697, 2025). "In addition, both PNPLA3 and TM6SF2 loci have been associated with the development of steatohepatitis, fibrosis, and cirrhosis and in the case of PNPLA3 also with HCC." (PMID 39142818, 2024). "The PNPLA3 polymorphism is associated with increased susceptibility to MASLD, disease progression to cirrhosis, and risk of developing HCC, and prior research supports the incorporation of the PNPLA3 genotype into prognostic scores for predicting the risk of disease progression." (PMID 39324073, 2024). "Previous studies have demonstrated that PNPLA3(148M) variation is associated with a variety of liver diseases, including MAFLD, non-alcoholic steatohepatitis (NASH), fibrosis, cirrhosis, and hepatocellular carcinoma (HCC), and increases the risk of liver-related death." (PMID 37753315, 2023). "The present study investigates if common missense functional variants p.I148M and p.E167K in PNPLA3 and TM6SF2 genes, respectively, associate with development of hepatic fibrosis and cirrhosis in a geographically novel cohort of Pakistani chronic hepatitis C (CHC) patients." (PMID 36028802, 2022). "PNPLA3 GG genotype and GGT were independently associated with cirrhosis." (PMID 35630668, 2022).
Cirrhosis (continued). "In addition, studies have pointed out that genetically-driven NAFLD-related genes such as PNPLA3 and TM6SF2 genes are associated with increased liver fat content and progression to NASH and cirrhosis." (PMID 35310993, 2022). "Concerning the PNPLA3 I148M variant, the exact molecular mechanisms leading to cirrhosis and HCC have not been established but the functional relevance was clarified in some aspects." (PMID 36499681, 2022). "Later studies, mainly in patients with hepatitis C virus-related cirrhosis, confirmed this finding, but independence from PNPLA3, a dominant risk factor, was not tested." (PMID 34640639, 2021). "Homozygous carriers of PNPLA3 rs738409[G] have a three-fold risk of steatohepatitis, and a four-fold risk of cirrhosis relative to non-carriers." (PMID 33804302, 2021). "The frequency of the PNPLA3 rs738409 minor (G) allele was significantly higher in patients with NASH cirrhosis than in the other two study populations, as well as in noncirrhotic NAFLD patients with respect to healthy controls." (PMID 29732362, 2018). "Only the PNPLA3, TM6SF2, and KLF6 SNPs were then selected to constitute the genetic risk score, participating according to the model which best fitted with their association to the risk of NASH cirrhosis." (PMID 29732362, 2018). "Analysis of ∼9,200 nonsynonymous sequence variants revealed a common missense substitution (rs738409, I148M) in PNPLA3 that is associated with the full spectrum of NAFLD, including liver fat content, steatohepatitis, cirrhosis, and hepatocellular carcinoma (5, –, 9)." (PMID 27013658, 2016). "Metabolic factors, such as diabetes, obesity, and hypertension, as well as common genetic polymorphisms in the PNPLA3 and TM6SF2 genes, influence the severity of underlying liver histology and, thus, are likely to impact on risk of developing cirrhosis and HCC." (PMID 27213358, 2016). "For example, a strong association of PNPLA3 rs738409, a single nucleotide polymorphism (SNP) in the patatin-like phospholipase domain-containing 3 (PNPLA3) gene, with liver fat content, fibrosis, cirrhosis and non-alcoholic fatty liver (NAFLD)-related hepatocellular carcinoma has been reported." (PMID 26847197, 2016). "The rs738409 variant in patatin-like phospholipase domain-containing 3 (PNPLA3) has been identified as conferring a significant risk for developing cirrhosis in relation to non-alcohol-related fatty liver disease and alcohol-related liver disease." (PMID 27888630, 2016). "Overall, 47.5% of the participants with predicted cirrhosis carried 2 risk alleles of PNPLA3 SNP rs2281135 compared to 21.2% of the non-cirrhotic participants (p = 0.03)." (PMID 26950933, 2016). "Neither univariate nor multivariate analysis showed the association of PNPLA3 genotype with cirrhosis (data not shown)." (PMID 25713769, 2015). "Therefore, in this study we focused on the association between PNPLA3 polymorphisms and the risk of HBV-related hepatic cirrhosis." (PMID 25337145, 2014). "Additionally, PNPLA3 GG accentuated the rate of cirrhosis onset among MASLD patients (aHR 23.3)." (PMID 39412170, 2025). "In a large UK Biobank cohort of more than 400 000 participants, 2398 of them developed cirrhosis, and the adjusted risk of cirrhosis was 17 times higher in individuals with excessive drinking, with obesity, and with PNPLA3 GG genotype, when compared to those without any of these 3 risk factors." (PMID 39412170, 2025). "This study demonstrates a significant association between PNPLA3 gene variants, particularly the rs738409 polymorphism, and the development of alcoholic liver disease (ALD), with a possible link to more advanced disease stages such as steatohepatitis and cirrhosis." (PMID 40831836, 2025). "For example, the genetic variant rs738409 (G) in the PNPLA3 gene was an independent risk factor for the development of HCC in patients with alcoholic cirrhosis but showed no influence in the progression of HCV-related cirrhosis to HCC." (PMID 39257588, 2024).